IL4 (interleukin 4)
Diseases named in the same sentence as IL4 in open-access papers (continued):
Sharing a sentence is not in itself a finding about the gene and the disease.
tuberculosis (continued). "We showed that the triggering of signal transducer and activator of transcription 6 (STAT6) in interleukin (IL)-4-activated human macrophages (M(IL-4)) prevents FM formation induced by pleural effusion from patients with tuberculosis." (PMID 33002063, 2020). "Higher values of T-cell associated mediators (IL-4, -5, -7, -13, -17, -12p70; RANTES/CCL5, TNF-α) and growth factors (PDGF, FGF, and TGF-β1) grouped together in participants with a tuberculosis dissemination score of zero." (PMID 31276515, 2019). "Where co-infection was shown to enhance susceptibility to TB, increased Th2 cytokines were implicated; as for instance in the case of IL-4 promoting alternatively activated macrophages (AAMs) that accumulated in the lungs, correlating with deficient innate anti-tuberculosis protection." (PMID 28192437, 2017). "Filarial infections are established early in life, induce increased IL-4 production are co-endemic with tuberculosis (TB)." (PMID 28658262, 2017). "It has been shown that the level of IL-4 secretion is related to tuberculosis pathogenesis and host immune homeostasis." (PMID 23936496, 2013). "Further investigation of the impact of IL-4 production on lymphocyte number and function in tuberculosis is needed to better understand this observation." (PMID 23527200, 2013). "Another study reported that elevated blood IL-4 levels in healthy individuals induced by contact with active tuberculosis patients for six months predicted the enhanced likelihood for these people to develop tuberculosis themselves." (PMID 23936496, 2013). "TST-positive tuberculosis patients had higher IL-4 and IL-10 values than healthy controls, though the difference was not statistically significant (q = 1.043, 0.748, P = 0.299, 0.456)." (PMID 23936496, 2013). "We analyzed the relationships between Treg cell enrichment and Mtb. specific cytokine (IFN-γ and IL-4) producing helper T cells among PTB patients (n = 21) who underwent anti-tuberculosis therapy and followed longitudinally." (PMID 23028594, 2012). "A major finding of our study is that serum levels of IL-4 were significantly lower in tuberculosis, compared with sarcoidosis." (PMID 22815689, 2012). "Median BAL levels of the Th2 cytokines IL-4 and IL-13 were significantly higher in sarcoidosis and tuberculosis compared to healthy BALs (p < 0.001)." (PMID 22815689, 2012). "In sera, tuberculosis patients had significantly lower levels of the Th2 cytokine interleukin-4 (IL-4) than those with sarcoidosis (p = 0.004)." (PMID 22815689, 2012). "As a group healthy volunteers had lower transcript levels for all the three target genes investigated compared to tuberculosis patients, (IL-4, p = 0.03; IFN-α, p = 0.009 and GATA-3, p = 0.04)." (PMID 22509293, 2012). "The 8 low expressers of IL-12Rβ2 mRNA (Low-C) had the highest transcript levels of IL-4 compared to the Low-T, (p = 0.01) & High-C (p = 0.02) group of tuberculosis patients and healthy volunteers examined, (p = 0.002)." (PMID 22509293, 2012). "Several human studies have shown that IL-4 production is increased in tuberculosis patients compared with controls." (PMID 19941997, 2010). "The ratio of IL-4 to IL-4δ2 affects the progression of latent to active tuberculosis." (PMID 38675618, 2024). "Interestingly, IL-4 is also important for the control of inflammation during tuberculosis, protecting against the lung pathology concurrent with an unchecked inflammatory response." (PMID 37764917, 2023). "Similarly, the concentration of IL-6 was significantly increased and IL-4 decreased in SA, and the concentrations of INF-γ, IL-2, IL-4 and IL-10 were significantly lower in tuberculosis, compared to those in healthy subjects." (PMID 36982159, 2023). "tuberculosis coinfections in Indian adults are associated with lower circulating levels of inflammatory cytokines, including IFN-γ, TNF-α, IL-17A, and IL-17F alongside increased type 2 cytokines IL-4, IL-5, and IL-13." (PMID 39816832, 2023).
tuberculosis (continued). "Therefore, we predicted central DEGs in the PPI network and noted strong interactions between TNF, IL-6, IL-10, IL-1β, CSF-2, IL-4, CXCL8, IFN-γ, IL-1α, and CXCL1, all of which are strongly associated with tuberculosis." (PMID 37818041, 2023). "The effect of IL-4 signalling on lymphocytic cells may be more profound than myeloid cells in tuberculosis." (PMID 34220793, 2021). "In contrast, the decision tree analysis showed that combined gene expression of IFN-γ, IL-2R, and IL4 differentiated tuberculosis patients (both PTB and EPTB) from healthy participants with sensitivity, specificity, and accuracy of 89.7%, 96.1%, and 92.7%, respectively." (PMID 32962082, 2020). "It is known that IL-4 and IL-13 cytokines act as inhibitors of the autophagic process, impairing antigen presentation, T cell clonal expansion, and consequently the organization of granulomas in tuberculosis." (PMID 26495323, 2015). "In human tuberculosis patients, the roles of Th2 cells and IL-4 are similarly controversial." (PMID 26000298, 2015). "It is therefore possible that the functions of the antigen induced CD4+CD25hiFoxP3+ Treg cells in tuberculosis have similar regulatory function as the naturally occurring Treg cells and may be mediated by IL-4 expression." (PMID 23826366, 2013). "IL-4 mRNA in PBMC has been associated with advanced pulmonary TB as well as a subgroup with increased antagonist IL-4δ2; the role of Th2 cytokines in human tuberculosis requires further investigation." (PMID 23527200, 2013). "In addition, we suggest that high expression of FasL triggers Vδ2+ T cell apoptosis, and increased IL-4 and IL-10 secretion induce an impairment of Vδ2+ T cell-mediated anti-tuberculosis immunity." (PMID 23936496, 2013). "The higher IL-4 levels observed in sarcoidosis may therefore also account for the peripheral antibody response which is stronger than that seen in tuberculosis." (PMID 22815689, 2012). "One previous study has quantified mRNA levels of IL-4 in sarcoidosis and tuberculosis granulomas within diseased lymph nodes and found that four out of eight tuberculosis samples expressed detectable amounts of IL-4 and/or IL-5 mRNA, compared with undetectable levels in six sarcoidosis samples." (PMID 22815689, 2012). "The best fit model found was log(P(Tuberculosis)/P(sarcoidosis)) = 1.214 + 8.884 * IL1 + 0.075 * IFN + 0.32 * IL12p70 + 0.039 * TNF − 0.097 * IL5 − 0.015 * IL8 − 0.73 * IL13 − 0.606 * IL10 − 2.404 * IL2 − 4.231 * IL4." (PMID 22815689, 2012). "Progression from latent to active tuberculosis may depend on the potential ratio of IL-4 to IL-4δ2." (PMID 38675618, 2024). "However, in a previous assay with IL-4 deficient BALB/C, another group of researchers showed the opposite effect, i.e., the lack of IL-4 aggravates M. tuberculosis infection, which reinforces the needed of balance between Th1 and Th2 responses in tuberculosis." (PMID 36678397, 2022). "IL-1β eradicates invading pathogens by activating neutrophils and macrophages; IL-4 inhibits the activation of macrophages and interferes with the clearance of Mtb by Th1 cells, which is an important factor for promoting the occurrence of tuberculosis and the recurrence of chronic infection." (PMID 35425720, 2022). "In humans, IL-4 may also have a determinant role in tuberculosis development." (PMID 36678397, 2022). "A study conducted among medical professionals showed that those individuals whose peripheral blood mononuclear cells synthesized IL-4 in response to M. tuberculosis infection in vitro subsequently developed an active form of TB within 2–4 years." (PMID 34835417, 2021). "In our study, we further determined the values of IL-4, IL-10 and other related cytokines specifically in anergic tuberculosis patients, which were significantly higher than in TST-positive tuberculosis patients and may be associated with the etiology of anergic tuberculosis." (PMID 23936496, 2013).
tuberculosis (continued). "This is perhaps best highlighted in TB where IL-4 severely attenuates protective immunity to M. tuberculosis." (PMID 23991011, 2013). "Th1 immune responses (IFN-γ, IL-12) are required for protection against infection with M. tuberculosis while a raised Th2-like cytokine profile (such as, IL-10, IL-4 and TGF-β) is implicated with disease progression in TB." (PMID 23320781, 2013). "The increased serum IL-4 levels in sarcoidosis may reflect a persistent and ongoing multi-system inflammatory allergic type response to an antigen not completely cleared by the immune system, in contrast to the lower levels seen in tuberculosis." (PMID 22815689, 2012). "Furthermore, the main difference we identified between sarocidosis and tuberculosis, ie serum IL-4 levels, remains statistically significant after correction for multiple comparisons even when only patients with acute untreated pulmonary sarcoidosis and active pulmonary tuberculosis were compared." (PMID 22815689, 2012). "The results indicated that these mRNAs were enriched in terms related to interleukin 4 (IL4) regulation, signaling adaptor activity, and pathways such as tuberculosis, platelet activation, and the pentose phosphate pathway." (PMID 38836231, 2024). "Thus, IL-4 may also be a promising therapeutic target for tuberculosis." (PMID 37327256, 2023). "In another study, IFN-γ, IL-4, IP-10, and TNF levels in plasma were able to discriminate tuberculosis patients from household contacts with high sensitivity." (PMID 32962082, 2020). "The effects of interleukin gene (IL4, IL6, IL10) on tuberculosis were assessed by logistic regression analysis under three genetic models, including dominant, recessive and log-additive models." (PMID 29662655, 2018). "In total, we found two results that withstood multiple testing correction: IL4 in pooled model and TLR2 for tuberculosis." (PMID 26524966, 2015). "With regards to tuberculosis, we are unaware of previous work investigating IL-13 BAL levels but increased IL-4 secretion from both CD4+ and CD8+ T-cells in active pulmonary tuberculosis has been shown compared to those with latent infection." (PMID 22815689, 2012). "However, the differences seen with IL-4 may form the basis of a broader serum cytokine profile to accurately distinguish sarcoidosis from tuberculosis; incorporating additional markers in a larger study might substantially improve on the 73% accuracy of the panel used here." (PMID 22815689, 2012). "Tuberculosis triggers a type 1 immune response characterized by IL-12, IFN-γ, and TNF-α production, while toxocariasis elicits a type 2 response, mediated by cytokines such as IL-4, IL-5, IL-13, and IL-33." (PMID 40943043, 2025). "In contrast, patients with treatment-resistant tuberculosis showed an increase in “Th0” cells because there was persistent production of IL-4 regardless of the presence or absence of treatment." (PMID 26495323, 2015). "The Vδ2+ T cell percentages in the BALF of all tuberculosis patients were lower than in their peripheral blood (P <0.05), and IL-4 and IL-10 concentrations in peripheral blood of anergic tuberculosis patients were higher than in TST-positive tuberculosis patients and healthy controls (P <0.05)." (PMID 23936496, 2013). "However, no study appears to have been done to compare the monocytes of tuberculosis patients and healthy controls in their in vitro MGC forming ability with particular reference to the relative roles of IL-4 and IL-10." (PMID 24147054, 2013). "One explanation for this is that Th2 cells may localize to the site of disease in tuberculosis but not so in sarcoidosis, leading to the higher serum IL-4 levels found in our sarcoidosis patients." (PMID 22815689, 2012). "Moreover, treatment of tuberculosis patients led to a (nonsignificant) decrease in IL4 expression when a validated reference gene was used." (PMID 20441576, 2010).
tuberculosis (continued). "However, although it is generally recognized that humoral immunity is not important for the control of tuberculosis, IL4-induced antibody response against M. bovis may be important for tuberculosis control in wild boar." (PMID 22848869, 2012). "Since pathology in TB typically involves inflammatory aggregates around infected cells, where TNF-α plays an important role, we predicted that IL-4 would inhibit the ability of cells to remove M. tuberculosis by apoptosis of infected cells, through the extrinsic pathway, which is activated by TNF-α." (PMID 21253484, 2011). "Th2 response characterized by IL-4 production, which is predominant during infection with M. tuberculosis, has been reported to be non-protective in TB." (PMID 21703025, 2011). "Therefore, we believe that an increased persistent level of IL-6 expression in the cohort of HIV/TB patients against the background of ART and reduced concentrations of IL-4 and IL-10 can serve as a possible marker of early detection of M. tuberculosis infection in HIV-infected individuals." (PMID 34835417, 2021). "IFN-γ, IP-10, IL2R, and CXCL-9 showed high expression in latent and active tuberculosis patients (p = 0.001), with a decrease in IL10 expression, and no statistical difference in IL-4 levels among all the groups (p = 0.999)." (PMID 32962082, 2020). "Indeed, Th2 lymphocyte subsets have been observed in lung tissue from patients with cavitary tuberculosis, compared with Th1 subsets in non-cavitary disease, suggesting that IL-4 might be an indicator of disease severity and that the Th2 environment can increase immunopathology." (PMID 20544012, 2010). "The ratio of IFN-γ/IL-10 and IFN-γ/IL-4 showed a significant increase after treatment in HIV negative TB cases but not in HIV positive TB cases which might indicate prolonged impairment of immune response to TB in HIV positive TB patients as compared to HIV negative tuberculosis patients." (PMID 24592945, 2014). "The higher level of IFN-γ/IL-4 and IFN-γ/IL-10 in HIV negative TB cases is expected where a Th1 type immune response dominates after clearance of the actively multiplying bacteria and resolution of the disease by the anti-tuberculosis treatment." (PMID 24592945, 2014). "We hypothesize that one such factor, IL-4, a cytokine whose expression appears to correlate with a poorer prognosis after M. tuberculosis infection when combined with TNF-α, may worsen TB-related pathology, possibly by biasing cell death towards necrosis instead." (PMID 21253484, 2011).
colon carcinoma (73 papers, 2000 to 2025). "GO and KEGG enrichment analyses indicated that the activity against colon cancer of THCQF was associated with the interleukin (IL)-4 and IL-3 signaling pathways." (PMID 35479514, 2022). "In the meantime, KEGG pathway enrichment indicated that the major mechanisms of THCQF inhibited colon cancer were associated with the interleukin (IL)-4 and IL-3 signaling pathways." (PMID 35479514, 2022). "Cognizant of these possibilities, the current study was designed to determine if murine M(IL4)s would affect the severity of disease in models of inflammation-associated colon cancer (CRC), infectious colitis and antigen-driven airways hypersensitivity." (PMID 34691050, 2021). "In the MC38‐HER2 colon cancer model, the combination of Fc–IL‐4 and HER2‐CAR‐T therapy resulted in 87% tumour eradication." (PMID 39739593, 2025). "Colon cancer stem cells autocrine produce and utilize IL-4 which enhances antiapoptotic protein expression to protect themselves from apoptosis in colorectal cancer." (PMID 38773979, 2024). "Blocking IL-4 signaling has been related to apoptotic stimulation of cancer stem-like cells, which suggests inducing IL-4 inhibition as possible therapeutic tools in colon carcinoma." (PMID 36552602, 2022). "Clinical studies have revealed that increased levels of IL4 are usually observed in various types of tumors, including colon carcinomas." (PMID 36362361, 2022). "In colon cancer, IL-4 secreted by CSCs is required for the maintenance of stemness and for inhibiting apoptosis." (PMID 36182945, 2022). "Elevated expression of IL4 and IL4 receptors has been demonstrated in various tumor cells, including lung, breast, pancreas, thyroid, and colon tumor cells." (PMID 36362361, 2022). "IL4 stimulates 3β-HSD activity in colon cancer cell line HT-29; however, the regulation of IL4-mediated HSD3B1 expression is not yet understood." (PMID 36362361, 2022). "Here, we demonstrated that administration of IL4 to an HT-29 colon cancer cell line induced high expression of HSD3B1 at the mRNA and protein levels." (PMID 36362361, 2022). "Results of earlier studies have shown that IL-4 facilitates fusion in cultured myocytes or that IL-4 promotes myogenic differentiation in colon carcinoma-bearing mice." (PMID 34051858, 2021). "Different inflammatory proteins are also suppressed in colon cancer tissues, including interleukin-4 (IL-4), IL-6, IL-18, TNF-α, and interferon gamma (IFN-γ)." (PMID 34163519, 2021). "Blocking of IL4R with IL4Rα antagonist or anti-IL4 neutralizing antibodies sensitized CD133-expressing colon cancer stem cells to conventional the chemotherapeutics oxaliplatin and 5-FU." (PMID 33419470, 2021). "IL-4/IL-4R in colon cancer cell lines Liu and colleagues found IL-4 and IL-13 increased nicotinamide adenine dinucleotide phosphate oxidase 1-related proliferation in HT-29 and DLD-1 human CC cells." (PMID 33450900, 2021). "After receptor binding, IL-4 and IL-13 can mediate tumor cell proliferation, survival, and metastasis in gastric or colon cancer." (PMID 33450900, 2021). "Todaro and colleagues discovered that stem-like colon tumor cells produced and utilized IL-4 to protect themselves from apoptosis, which signposts that the correlation of IL-4 with stem-like tumor cells in pancreatic cancer has to be taken into account." (PMID 33804263, 2021). "IL-4/IL-13 increased the proliferation of human colon cancer cells dependent on NAPDH oxidase 1, endometriotic stomal cells, mast cells, human lymphoblasts, fibroblasts, fibro/adipogenic progenitors (FAPs)." (PMID 34863091, 2021). "This review summarizes the results about the role of IL-4/IL-13 and their receptors in gastric and colon cancer." (PMID 33450900, 2021). "It was reported that IL-4 and IL-13 inhibited colon cancer cell-cell adhesion by down-regulation of E-cadherin and CEA molecules." (PMID 32832545, 2020).